DLEC1 (DLEC1 cilia and flagella associated protein)
Description:
Essential for spermatogenesis and male fertility (By similarity). May play an important role in sperm head and tail formation (By similarity). May act as a tumor suppressor by inhibiting cell proliferation.
Synonyms: DLC-1; DLC1; CFAP81; FAP81; F56
Tractability: No criterion of Open Targets' tractability assessment is met for any kind of drug.
Gene: Protein-coding gene on chromosome 3 (38,039,205 to 38,124,025, forward strand). Ensembl gene ENSG00000008226.
Subcellular location: Cytoplasm
Subcellular location (Human Protein Atlas): Cytosol
Gene Ontology:
Molecular function: alpha-tubulin binding; beta-tubulin binding; protein binding; tubulin binding
Biological process: defense response to tumor cell; negative regulation of cell population proliferation; spermatogenesis
Cellular component: cytoplasm; cytosol; cilium
Genetic constraint (gnomAD): Loss-of-function variants: 146 observed, 206 expected, observed/expected ratio (o/e) 0.71, 90% interval 0.62 to 0.81. The upper end of that interval is the gene's LOEUF score, 0.81, which puts it in group 3 of 6, group 1 being the genes least tolerant of losing a copy. Missense variants: 2,227 observed, 2,316.2 expected, observed/expected ratio (o/e) 0.96, 90% interval 0.93 to 1. Synonymous variants: 894 observed, 908.25 expected, observed/expected ratio (o/e) 0.98, 90% interval 0.93 to 1.04.
Homologues: Orthologues: chimpanzee DLEC1 (95% identical), macaque DLEC1 (93% identical), dog DLEC1 (77% identical), pig DLEC1 (75% identical), guinea pig DLEC1 (74% identical), mouse Dlec1 (70% identical), rat Dlec1 (70% identical), tropical clawed frog dlec1 (42% identical). Paralogues in human: HYDIN (17% identical), CFAP47 (12% identical).
Diseases named in the same sentence as DLEC1 in open-access papers:
DLEC1 is named in the same sentence as 48 diseases in open-access papers, as found by Europe PMC text mining. Sharing a sentence is not in itself a finding about the gene and the disease. The quoted sentences say what the papers report.
lung carcinoma (9 papers, 2008 to 2024). "Exposure to smoky coals was associated with higher DLEC1 methylation in plasma and tissue samples from Chinese lung cancer patients, implying that air pollution-induced DLEC1 methylation could influence cancer etiology." (PMID 33153431, 2020). "DLEC1 is a common tumor suppressor gene that is often downregulated or lost in lung cancer due to promoter hypermethylation." (PMID 26550574, 2015). "Many studies showed that methylation of the DLEC1 gene correlates with poor prognosis in lung cancer and ovarian cancer." (PMID 25574068, 2014). "In any case, concordant methylation of MLH1 with DLEC1 or RASSF1A is a valuable prognostic indicator in lung cancer." (PMID 18594535, 2008). "In this study, we demonstrate for the first time that the DLEC1 promoter is methylated in lung cancer." (PMID 18594535, 2008). "Three of them (RASSF1A, CDKN2A, and DLEC1) were found only in lung cancer patients." (PMID 31752198, 2019). "Expression of DLEC1 was assessed by RT–PCR in five lung cancer cell lines." (PMID 18594535, 2008). "In this study, we investigated if promoter hypermethylation of DLEC1 is found in lung cancer and whether it has any prognostic significance." (PMID 18594535, 2008). "Moreover, the expression of DLEC1 enhances primary cilia formation in A549 lung cancer cells." (PMID 33144677, 2020). "However, it has been previously demonstrated that DLEC1 RNA expression was lost in eight of 30 primary lung cancers and that this was not due to gene mutations." (PMID 18594535, 2008). "The methylation levels of eight genes (CALCA, HOXA9, RASSF1A, CDKN2A, DLEC1, CDH13, PITX2, and WT1) in ctDNA were significantly higher in lung cancer patients than in non-lung cancer patients." (PMID 31752198, 2019). "Deleted in lung and esophageal cancer 1 (DLEC1), a 3p22 cluster genes, was first identified as a TSG in esophageal and lung cancers." (PMID 23050586, 2012). "Among these identified sequences, one of particular interest is DLEC1, a candidate TSG previously identified in lung cancer." (PMID 19156137, 2009). "No prognostic value was detected for DLEC1 methylation in our study or in a research report studying colorectal cancer; however, a study in lung cancer provided the opposite view." (PMID 26550574, 2015). "Promoter hypermethylation has been shown to be responsible for silencing of DLEC1 in ovarian cancer and in nasopharyngeal carcinoma but there has been no comprehensive methylation analysis reported for lung cancer." (PMID 18594535, 2008). "While DLEC1 was expressed in normal lung tissue, no expression was detected in the A427, A549 and H1299 lung cancer cell lines." (PMID 18594535, 2008).
breast carcinoma (5 papers, 2007 to 2026). "In vitro and in vivo experiments on breast cancer (BrCa) cell lines were conducted to explore the functions and mechanisms of DLEC1." (PMID 42002658, 2026). "Remarkably, DLEC1 was methylated in breast cancer as well as pre-invasive lesions but rarely in normal breast tissues, indicating its potential as an epigenetic marker for early tumors." (PMID 23050586, 2012). "Downregulation of DLEC1 by promoter methylation has been found in multiple cancers, including nasopharyngeal, ovarian, lung, hepatocellular, gastric, renal, and breast carcinomas, suggesting its potential as a broad TSG." (PMID 23050586, 2012). "Expanding WGS to ClinVar genes also identified a LoF mutation in the tumor suppressor gene DLEC1 in a BRCA1-mutant patient (BRCA1.73); the function of the encoded DLEC1 protein is not well defined but has been found to be lost in breast cancer." (PMID 26023681, 2015). "Among ovarian carcinomas, only a handful such genes have been shown to exhibit DNA promoter hypermethylation, including the Insulin-like growth factor binding protein-3 (IGFBP-3), the Deleted in Lung and Esophageal Cancer 1 (DLEC1), and the breast cancer gene BRCA1." (PMID 17623056, 2007).
nasopharyngeal carcinoma (4 papers, 2008 to 2015). A carcinoma arising from the nasopharyngeal epithelium. "In other tumor types, DLEC1 was found to be methylated in the serum of 25% of nasopharyngeal carcinoma patients and in the plasma of 35.9% of NSCLC patients." (PMID 26550574, 2015). "Recently, DLEC1 was reported to be frequently downregulated by methylation in ovarian and nasopharyngeal cancer." (PMID 19156137, 2009). "Deleted in lung and esophageal cancer 1 (DLEC1) is a tumor-suppressor gene which suppresses tumor growth or reduces the invasiveness of cancer cells and promoter hypermethylation has been shown to be responsible for the silencing of DLEC1 in ovarian cancer and nasopharyngeal carcinoma." (PMID 25574068, 2014).
ovarian carcinoma (4 papers, 2007 to 2021). A malignant neoplasm originating from the surface ovarian epithelium. "The loss of DLEC1 expression in ovarian cancer is related to promoter hypermethylation and histone hypoacetylation but not to loss of chromosome 3p22.3." (PMID 25574068, 2014). "We analysed the expression of frequently downregulated tumour suppressor genes in immune subtype (ie DIRAS3, PEG3, and DLEC1) in the human ovarian cancer cell line SKOV3 and found DIRAS3 was most highly expressed." (PMID 33522069, 2021). "Previous research demonstrated the loss of DLEC1 expression in ovarian cancer and the suppression of ovarian cancer cell growth by DLEC1 reexpression." (PMID 25574068, 2014).
colon cancer (3 papers, 2008 to 2016). "Moreover, the epigenetic demethylation and up-regulation of deleted in lung and esophageal cancer 1 (DLEC1), a tumor suppressor gene, could be involved in the inhibitory effect of curcumin on anchorage-independent growth of human colon cancer cells." (PMID 27529277, 2016). "It has recently been shown that DLEC1 and MLH1 are also subject to long-range epigenetic regulation in colon cancer." (PMID 18594535, 2008).
gastric cancer (3 papers, 2009 to 2025). A primary or metastatic malignant neoplasm involving the stomach. "In our study, a multivariate Cox proportional hazards model indicated that DLEC1 methylation was an independent risk factor for recurrence in gastric cancer." (PMID 25574068, 2014). "In this study, we determined methylation of DLEC1 promoter by quantitative methylation-specific PCR and demonstrated that DLEC1 promoter was hypermethylated in Chinese gastric cancer patients." (PMID 25574068, 2014). "Patients with DLEC1-hypermethylated gastric cancer had significantly higher recurrence rate than those with DLEC1-hypomethylated gastric cancer (P = 0.025; hazard ratio = 2.43)." (PMID 25574068, 2014). "In summary, we found that DLEC1 is frequently silenced by promoter methylation in colorectal and gastric cancers in a tumour-specific manner." (PMID 19156137, 2009). "The frequent silencing of DLEC1 by methylation in colon and gastric cancer cell lines as well as primary tumours suggested that DLEC1 is a potential tumour suppressor for these tumours." (PMID 19156137, 2009). "The CRC cell line HCT116 and gastric carcinoma cell line MKN45 with silenced DLEC1 were transfected with DLEC1-expressing vector pcDNA3.1-DLEC1." (PMID 19156137, 2009). "However, it would be worthy further exploring the possible use of DLEC1 methylation as a predictor for recurrence in gastric cancer." (PMID 25574068, 2014). "The purpose of our study is to investigate the relationship of DLEC1 methylation with clinicopathologic variables and determine whether DLEC1 methylation has any prognostic significance in patients with gastric cancer." (PMID 25574068, 2014). "The DLEC1 methylation was compared to the clinicopathological variables of gastric cancer." (PMID 25574068, 2014). "In addition, the ectopic expression of DLEC1 significantly suppressed colorectal and gastric carcinoma cell clonogenicity." (PMID 19156137, 2009). "Furthermore, promoter hypermethylation of DLEC1 has also been found in gastric cancer." (PMID 25574068, 2014). "Thus, methylation of DLEC1 may be a valuable indicator for recurrence in gastric cancer." (PMID 25574068, 2014). "Together with our results of DLEC1 methylation in CRC and gastric cancers, DLEC1 is likely to be inactivated in a wide range of tumours by promoter methylation and plays an important role in multiple tumorigenesis." (PMID 19156137, 2009). "By MSP, DLEC1 methylation was detected in 83% (10 out of 12) of CRC and 100% (17 out of 17) of gastric cancer cell lines, with complete methylation detected in most cell lines, whereas no methylation was seen in the normal colon epithelial cell line CCD-841." (PMID 19156137, 2009). "This is the first report to identify DLEC1 as a methylated candidate TSG for CRC and gastric cancer." (PMID 19156137, 2009). "In contrast, DLEC1 was silenced or downregulated in six of seven CRC and 15 of 17 gastric cancer cell lines." (PMID 19156137, 2009). "Our results indicated that DLEC1 is a functional TSG for CRC and gastric cancers, but is frequently inactivated by methylation-mediated silencing in these tumours." (PMID 19156137, 2009). "Here, we provided solid evidence that DLEC1 is also frequently methylated and acts as a functional TSG in CRC and gastric cancers." (PMID 19156137, 2009). "Together with earlier results of DLEC1 reactivation after genetic demethylation in DKO cells, these results showed that methylation of the DLEC1 promoter directly leads to its silencing in CRC and gastric cancers." (PMID 19156137, 2009). "Second, we had not measured DLEC1 RNA expression and DLEC1 protein expression in tissues of gastric cancer." (PMID 25574068, 2014). "The tumour-specific methylation of DLEC1 in CRC and gastric cancers indicates that it could be used for such purposes in future." (PMID 19156137, 2009). "Thus, promoter methylation of DLEC1 is a frequent and tumour-specific epigenetic abnormality in CRC and gastric cancer." (PMID 19156137, 2009).
colorectal cancer (2 papers, 2008 to 2015). A primary or metastatic malignant neoplasm that affects the colon or rectum. "The two genes, which were analysed in both studies, DLEC1 and its neighbour PLCD1, are silenced through DNA methylation and H3-K9 dimethylation in colorectal cancer whereas in bladder cancer they are silenced through histone H3-K9 trimethylation." (PMID 18594535, 2008).
lung adenocarcinoma (2 papers, 2020 to 2022). A carcinoma that arises from the lung and is characterized by the presence of malignant glandular epithelial cells. "Next, we investigated the effect of expression of DLEC1 on primary cilia formation in A549 lung adenocarcinoma cells." (PMID 33144677, 2020). "DLEC1 expression also enhanced primary cilia formation and cilia length in A549 lung adenocarcinoma cells." (PMID 33144677, 2020).
lymphoma (2 papers, 2012 to 2013). A malignant (clonal) proliferation of B- lymphocytes or T- lymphocytes which involves the lymph nodes, bone marrow and/or extranodal sites. "Promoter CpG methylation was frequently detected in 80% (20/25) of lymphoma cell lines and correlated with DLEC1 downregulation/silencing." (PMID 23050586, 2012). "In this study, we examined the expression and methylation status of DLEC1 in lymphoma cell lines and tissues, and evaluated its potential as a tumor marker for the early detection of hematologic tumors." (PMID 23050586, 2012). "DLEC1 unmethylated alleles and ANKRD30A methylated alleles detected in different types of normal and lymphoma samples indicated the reliability of these samples." (PMID 23050586, 2012). "More molecular studies on the tumor suppressive functions of DLEC1 in lymphoma pathogenesis are needed." (PMID 23050586, 2012). "Here, we report that DLEC1 is frequently silenced by promoter methylation both in lymphoma cell lines and primary lymphomas, but seldom in normal lymph nodes and PBMCs." (PMID 23050586, 2012). "Remarkably, DLEC1 is specifically methylated in sera of HL patients, suggesting its potential as an epigenetic biomarker for the non-invasive diagnosis of lymphomas." (PMID 23050586, 2012). "Of 58 lymphoma tissues, DLEC1 methylation was detected in 5/6 (83%) BL, 16/30 (53%, one weak) HL, 1/10 (10%) DLBCL, 6/8 (75%) NL, and 4/4 (100%, two weak) follicular lymphoma (FL) tumor samples, while no methylation was detected in normal lymph node samples." (PMID 23050586, 2012). "Our results suggest that epigenetic silencing of DLEC1 is important for lymphoma pathogenesis." (PMID 23050586, 2012). "We next investigated DLEC1 methylation in different types of primary lymphomas." (PMID 23050586, 2012). "Thus, methylation-mediated silencing of DLEC1 plays an important role in multiple lymphomagenesis, and may serve as a non-invasive tumor marker for lymphoma diagnosis." (PMID 23050586, 2012). "DLEC1 methylation showed a relatively low frequency in DLBCL samples, compared to other lymphoma types." (PMID 23050586, 2012). "This study identifies the frequent epigenetic inactivation of DLEC1 in various lymphomas and demonstrates its potential as a non-invasive tumor marker for the detection of lymphomas." (PMID 23050586, 2012). "DLEC1 methylation was also frequently detected in 32 out of 58 (55%) different types of lymphoma tissues, but not in normal lymph nodes." (PMID 23050586, 2012). "We examined the expression of DLEC1 by semi-quantitative reverse transcription (RT)-PCR, and evaluated the promoter methylation of DLEC1 by methylation-specific PCR (MSP) and bisulfite genomic sequencing (BGS) in common lymphoma cell lines and tumors." (PMID 23050586, 2012). "DLEC1 was highly expressed in the normal lymph node, PBMC samples, as well as human adult testis and bone marrow tissues, but silenced or reduced in 33% (2/6) DLBCL, 50% (1/2) PTCL, 100% (5/5) BL, 86% (6/7) HL, and 67% (2/3) NL cell lines, indicating that DLEC1 is a candidate TSG for lymphomas." (PMID 23050586, 2012).
male infertility (2 papers, 2020 to 2021). The inability of the male to effect fertilization of an ovum after a specified period of unprotected intercourse. "Furthermore, knockout of FAP81/Dlec1 in mouse causes male infertility, but due to aberrant spermatogenesis manifested by the production of a low number of mature sperm cells with abnormal morphology, including head shape malformation and short flagellum." (PMID 33809498, 2021). "Dlec1 deletion caused male infertility due to impaired spermatogenesis." (PMID 33144677, 2020). "Of these, Plcd1 and Acaa1b are not required for male fertility in mice, indicating that Ctdspl, Vill, Dlec1, and Slc22a14 are candidate genes responsible for male infertility." (PMID 33144677, 2020). "Toward the identification of the gene responsible for male infertility in olt/olt mice, we investigated the expression profiles of candidate genes (Dlec1, Vill, and Ctdspl) in various mouse tissues using reverse transcription-polymerase chain reaction (RT-PCR)." (PMID 33144677, 2020).
non-small cell lung carcinoma (2 papers, 2008 to 2011). A group of at least three distinct histological types of lung cancer, including non-small cell squamous cell carcinoma, adenocarcinoma, and large cell carcinoma. "This study set out to investigate promoter methylation in the deleted in lung and oesophageal cancer 1 (DLEC1), MLH1 and other 3p genes in 239 non-small cell lung carcinomas (NSCLC)." (PMID 18594535, 2008).
squamous cell carcinoma (2 papers, 2008 to 2020). A carcinoma arising from squamous epithelial cells. "However, an abnormal methylation profile (like DLEC1 hypermethylation) is significantly linked to head and neck, ovarian, lung, renal, nasopharyngeal, oral, adrenocortical, hepatocellular, esophageal, gastric, and squamous cell carcinoma." (PMID 33153431, 2020).
uterine fibroids (2 papers, 2012 to 2024). "Then, we analyzed the promoter region of another tumor suppressor gene, DLEC1, in uterine leiomyoma and myometrial samples from 7 subjects." (PMID 22428009, 2012). "Uterine leiomyoma tissues demonstrated a dense methylation pattern at the DLEC1 promoter region in 5 of the 7 subjects." (PMID 22428009, 2012). "The DLEC1 promoter region contains a CpG island in the first exon, and we demonstrated here that methylation of this CpG is responsible for the repression of DLEC1 expression in uterine leiomyoma." (PMID 22428009, 2012). "In the future, we plan to characterize the biological function of DLEC1 in uterine leiomyoma." (PMID 22428009, 2012). "Our analysis revealed a strong association between silencing of DLEC1 expression and promoter hypermethylation in uterine leiomyoma; in addition, treatment of addition of cultured primary uterine leiomyoma smooth muscle cells with a DNMT inhibitor restored DLEC1 expression." (PMID 22428009, 2012). "To validate that DNA methylation leads to gene silencing of the tumor suppressor genes KLF11, DLEC1, and KRT19, we assessed mRNA levels in vivo using real-time RT-PCR in uterine leiomyoma and matched myometrial tissues." (PMID 22428009, 2012).
Azoospermia (1 paper, 2020). Absence of any measurable level of sperm,whereby spermatozoa cannot be observed even after centrifugation of the semen pellet. "The human DLEC1 is a possible candidate for causative genes for idiopathic azoospermia or teratozoospermia." (PMID 33144677, 2020). "Since many reports suggest that DLEC1 acts as a tumour repressor, this study might provide a clue to elucidating the link between azoospermia and cancer." (PMID 33144677, 2020).
Bardet-Biedl syndrome (1 paper, 2020). A ciliopathy with multisystem involvement. "In addition, DLEC1 interacted with tailless complex polypeptide 1 ring complex (TRiC) and Bardet–Biedl Syndrome (BBS) protein complex subunits, as well as α- and β-tubulin." (PMID 33144677, 2020).
bladder cancer (1 paper, 2008). "In bladder cancer there is also evidence of such long-range epigenetic regulation around the DLEC1 gene, but here the predominant mechanism is gene silencing through histone methylation rather than CpG methylation, and MLH1 was not analysed." (PMID 18594535, 2008).